ZSCAN16-AS1 (ZSCAN16 antisense RNA 1)
Gene: Long non-coding RNA gene on chromosome 6 (28,008,599 to 28,137,319, reverse strand). Ensembl gene ENSG00000269293.
Gene Ontology:
Biological process: RNA processing
Cellular component: nucleolus